IL17A (interleukin 17A)
Diseases named in the same sentence as IL17A in open-access papers (continued):
Sharing a sentence is not in itself a finding about the gene and the disease.
musculoskeletal disease (6 papers, 2016 to 2025). "IL-17A is a key cytokine associated with inflammation and tissue remodeling in numerous musculoskeletal diseases, and thus, we sought to determine the role of IL-17A in the immunopathogenesis of frozen shoulder." (PMID 34544860, 2021). "As IL-17A is already a clinical target in other inflammatory (musculoskeletal) diseases, inhibition of IL-17A-induced gene expression was investigated." (PMID 34054865, 2021).
peripheral neuropathy (5 papers, 2019 to 2025). A disorder affecting the peripheral nervous system. "Therefore, the results from the current data provide the rationale for performing future studies to examine whether specifically blocking the spinal actions of IL-17A also suppresses allodynia from peripheral neuropathy." (PMID 31763376, 2019). "These variables showed that nearly 50% of the variation in the data, including pro-inflammatory IL-6, IL-17A, TNF-α, and LPS, contributed significantly to peripheral neuropathy." (PMID 41264657, 2025).
benign tumor (3 papers, 2016 to 2022). "The concentration of IL-17A in plasma of OC patients was higher (p < 0.0001) than that in both benign tumors and control group (n = 10)." (PMID 32148497, 2020).
Hematologic cancer (3 papers, 2020 to 2022). "Furthermore, Severe-Death hematologic cancer patients showed a trend to increased production of IL-17A, similar to what is observed in individuals from the general population infected by SARS-CoV-2 and other SARS viruses." (PMID 36700209, 2022).
IL17A also shares sentences with these, for which no sentence is quoted: staphylococcus aureus infection (69 papers); chronic periodontitis (51); cytomegalovirus infection (38); legionellosis (32); intestinal inflammation (24); herpesvirus infection (23); Kaposi's sarcoma (22); acute myocardial infarction (21); idiopathic pulmonary fibrosis (21); African trypanosomiasis (20); Epstein-Barr virus infection (20); measles (20); human papillomavirus infection (19); alcoholism (18); mental disorder (14); stable angina (14); vitamin D deficiency (12); American trypanosomiasis (11); chronic rhinosinusitis (11); upper respiratory tract infections (11); Yersinia infection (11); chronic hepatitis (10); encephalomyelitis (10); prion disease (10); cardiac hypertrophy (9); diabetic cardiomyopathy (9); head and neck cancer (9); nicotine addiction (9); chronic heart failure (8); head and neck squamous cell carcinoma (8).
A further 640 diseases each share a sentence with IL17A in 8 papers or fewer.